EEF1DP3 (eukaryotic translation elongation factor 1 delta pseudogene 3)
Gene: Transcribed unprocessed pseudogene on chromosome 13 (31,952,580 to 31,953,361, forward strand). Ensembl gene ENSG00000229715.
Diseases named in the same sentence as EEF1DP3 in open-access papers:
EEF1DP3 is named in the same sentence as 3 diseases in open-access papers, as found by Europe PMC text mining. Sharing a sentence is not in itself a finding about the gene and the disease. The quoted sentences say what the papers report.
Hypertension (1 paper, 2023). The presence of chronic increased pressure in the systemic arterial system. "Still, restricting the GRS to one single SNP per gene (rs17035646 for CASZ1 and rs77270397 for EEF1DP3, FRY-AS1) led to similar findings, i.e., the lack of association between the short GRS and hypertension control." (PMID 37479854, 2023).
EEF1DP3 also shares sentences with these, for which no sentence is quoted: breast carcinoma (1 paper); mammary tumor (1).